OTUB1 (OTU deubiquitinase, ubiquitin aldehyde binding 1)
Diseases named in the same sentence as OTUB1 in open-access papers (continued):
Sharing a sentence is not in itself a finding about the gene and the disease.
prostate carcinoma (14 papers, 2015 to 2025). A carcinoma that arises from epithelial cells of the prostate gland. "GO/KEGG and GSEA analyses were performed to examine the underlying mechanisms of UBE2M and OTUB1 in prostate cancer." (PMID 35864871, 2022). "Prostate cancer cells transfected with OTUB1 shRNA exhibited delayed tumor growth, reduced tumor size, and metastasis in a mouse xenograft model." (PMID 35884607, 2022). "In vitro studies have demonstrated that OTUB1 promotes prostate cancer invasion via RhoA activation." (PMID 35884607, 2022). "OTUB1 is overexpressed in human cancers and acts to suppress ferroptosis of prostate cancer by promoting SLC7A11 stability." (PMID 35864871, 2022). "OTUB1 activates RhoA to promote prostate cancer cell invasion and promote tumorigenesis in prostate cancer." (PMID 33498168, 2021). "To identify the possibility of targeting prostate cancer with OTUB1/Cyclin E1 axis, we treated PC3 cell with RO-3306, a Cyclin E1/CDK2 related inhibitor, in the range dose of 0, 340 nM, 1 uM, 2 uM, 3 uM, and 5 uM." (PMID 33537306, 2020). "After increasing the expression of OTUB1, the proliferation ability of prostate cancer cells was significantly enhanced (P < 0.01)." (PMID 33537306, 2020). "The results of RO-3306 treatment are the direct evidence of targeting OTUB1/Cyclin E1 axis for prostate cancer." (PMID 33537306, 2020). "The effect of OTUB1 expression level on the migration ability of prostate cancer PC3 and C4-2 cells was observed." (PMID 33537306, 2020). "Here, our study shows that OTUB1 deubiquitinates and stabilizes Cyclin E1 to promote the progression, migration, and proliferation of prostate cancer." (PMID 33537306, 2020). "To further identify the deubiquitinating enzymes OTUB1 driving the prostate cancer progression, we conducted subsequent experiments and assays." (PMID 33537306, 2020). "Although our research found that the deubiquitinase OTUB1 promotes the stability of Cyclin E1 and the progression of prostate cancer, the specific mechanism of OTUB1 mediated function of Cyclin E1 remains to be further studied." (PMID 33537306, 2020). "Our RNAi screening identified OTUB1 as an important regulator of prostate cancer cell invasion through the modulation of RhoA activation." (PMID 25623341, 2015). "OTUB1 also promotes tumorigenesis in vivo in good agreement with the overexpression observed in prostate cancer tumors." (PMID 25623341, 2015). "We found that OTUB1 plays a critical role not only in the AR-dependent but also AR-independent cell invasion of prostate cancer cells in vitro and in vivo through the modulation of RhoA activity." (PMID 25623341, 2015). "In order to validate these observations as general phenomena in prostate cancer cells, we analyzed the effects of OTUB1 in the androgen-insensitive PCa cell line, PC3." (PMID 25623341, 2015). "Similar effects were observed using 22Rv1 prostate cancer cells supporting the role of OTUB1 in the regulation of prostate cancer cells invasion." (PMID 25623341, 2015). "Prostate cancer xenografts expressing reduced levels of OTUB1 exhibit reduced tumor growth and reduced metastatic dissemination in vivo." (PMID 25623341, 2015).
prostate carcinoma (continued). "In this study we have demonstrated that OTUB1 protein levels are elevated in prostate cancer and contribute to the induction of cell invasion through a mechanism that involves the activation of RhoA." (PMID 25623341, 2015). "We found that in prostate cancer cells, OTUB1 has the capacity to modulate cell invasion of both AR+ and AR- cells in a manner that seems to be dependent on the presence of an intact active site." (PMID 25623341, 2015). "We next analyzed OTUB1 expression in prostate cancer by immunohistochemistry using tissue microarrays (TMAs)." (PMID 25623341, 2015). "Here, we provide the first demonstration that OTUB1 protein levels are altered in human prostate cancer and that downregulation of OTUB1 expression limits tumorigenesis in vivo." (PMID 25623341, 2015). "OTUB1 mediates prostate cancer cell invasion through RhoA activation and promotes tumorigenesis in vivo." (PMID 25623341, 2015). "In summary, we demonstrate that OTUB1-mediated activation of RhoA promotes cell invasion of prostate cancer cells." (PMID 25623341, 2015). "Further, OTUB1 is one of the most abundant deubiquitinases in cells and can act as an oncogene in several types of cancers, including lung, breast, gastrointestinal, and prostate cancers, as well as glioma." (PMID 35159073, 2022). "Importantly, aberrant upregulation of OTUB1 can enhance progression of multiple cancers including bladder cancer, prostate cancer and hepatocellular carcinoma." (PMID 34773364, 2021). "In prostate cancer, OTUB1 can block the ubiquitination of cyclin E1 and keep it stable." (PMID 34773364, 2021). "Additionally, it was reported that OTUB1 knockdown inhibits prostate cancer progression whereas OTUB1 upregulation has the opposite effect." (PMID 34773364, 2021). "The prognosis of patients with prostate cancer may be improved when the connection between OTUB1 and Cyclin E1 are interrupted or disturbed." (PMID 33537306, 2020). "Interfering with the contact between OTUB1 and Cyclin E1 might provide a potential therapy for prostate cancer." (PMID 33537306, 2020). "In order to identify whether clinical data was consistent with the database, we collected clinical prostate cancer tissue and immunohistochemical staining was performed with OTUB1 and ki-67 antibody." (PMID 33537306, 2020). "The OTUB1/Cyclin E1 axis may serve as a potential therapeutic target for patients with prostate cancer." (PMID 33537306, 2020). "So far, we have a lot of evidence to identify the hypothesis that OTUB1 promotes the progression and proliferation of prostate cancer via mediating and stabling Cyclin E1." (PMID 33537306, 2020). "OTUB1 mediates prostate cancer tumorigenesis and invasion through RhoA activation." (PMID 31737118, 2019). "Besides, the analysis of prostate cancer clinical samples shows that OTUB1 is overexpressed in localized tumor as compared to normal prostate epithelial cells." (PMID 25623341, 2015). "Moreover, overexpression of the protease inactive OTUB1-C91S mutant also resulted in diminished invasiveness, supporting the regulatory role of OTUB1 in prostate cancer cell invasion." (PMID 25623341, 2015). "Thus, our results would support the investigation of drugs targeting the catalytic activity of OTUB1 as potential therapy for advance prostate cancer." (PMID 25623341, 2015).
prostate carcinoma (continued). "RhoA activity was measured in relation with OTUB1 effects on prostate cancer cell invasion." (PMID 25623341, 2015). "The results further illustrated that OTUB1 regulated the expression and function of Cyclin E1 in vivo, and targeting OTUB1/Cyclin E1 axis might provide a potential therapeutic method for these patients with prostate cancer." (PMID 33537306, 2020). "Taken together, SNHG17 is very likely to influence immune infiltration by upregulating the expression of OTUB1 and UBE2M in prostate cancer." (PMID 35864871, 2022). "Previous studies found the effect of OTUB1 on prostate cancer, which showed that there was no significant deviation in PCa proliferation between decreased OTUB1 and the control group." (PMID 33537306, 2020). "Additionally, we observed that the expression of SNHG17, UBE2M, and OTUB1 was significantly correlated with a decreased infiltrating level of immune cells, indicating the immunological role of SNHG17 and its ceRNA regulatory network in prostate cancer." (PMID 35864871, 2022).
bladder cancer (13 papers, 2021 to 2025). "Kaplan–Meier survival analysis confirmed that bladder cancer patients with low OTUB1 expression had significantly superior overall survival compared to those with high OTUB1 expression." (PMID 37497216, 2023). "It has been found that OTUB1 can stabilize activating transcription factor 6α (ATF6α) in response to endoplasmic reticulum stress and promote bladder cancer progression." (PMID 37497216, 2023). "OTUB1 expression is markedly elevated in human bladder cancers; knockdown of OTUB1 expression diminishes endogenous SLC7A11, which subsequently enhances ROS-mediated ferroptosis in bladder cancer cell lines." (PMID 36505448, 2022). "The deubiquitinating enzyme OTUB1 is known to participate in the classical RNF8 pathway for DNA damage repair and is associated with esophageal cancer, bladder cancer." (PMID 35110531, 2022). "Additionally, some studies reported that OTUB1 promotes the progression of bladder cancer through its interaction with ATF6, and that ATF6 could facilitate cervical cancer cell growth and migration through the MAPK pathway, resulting in poor cancer prognosis." (PMID 35222510, 2021). "OTUB1 interacts with ATF6 and enhances its stability by inhibiting ubiquitination, thereby promoting the migration and proliferation of bladder cancer cells." (PMID 35959432, 2022). "It has been reported that OTUB1, P4HB, and EHMT2 could regulate the malignant phenotype of bladder cancer cells via the ERS related URP pathway." (PMID 35004850, 2021).
esophageal squamous cell carcinoma (10 papers, 2019 to 2025). Esophageal squamous cell carcinoma (ESCC) is a type of esophageal carcinoma (EC) that can affect any part of the esophagus, but is usually located in the upper or middle third. "With a tail-vein injection model, the authors showed OTUB1 promotes lung metastasis of esophageal squamous cell carcinoma cells in vivo." (PMID 38264570, 2023). "OTUB1 also facilitates metastasis of esophageal squamous cell carcinoma (ESCC) by promoting snail protein stability." (PMID 36369321, 2023). "OTUB1 is overexpressed in esophageal squamous cell carcinoma and correlates with the level of SNAIL." (PMID 38264570, 2023). "Many previous researches have shown that OTUB1 is frequently up-regulated in many cancers, such as esophageal squamous cell carcinoma and colon cancer." (PMID 33537306, 2020). "However, OTUB1 can facilitate the development of esophageal squamous cell carcinoma by stabilizing the SNAIL protein." (PMID 39227585, 2024). "OTUB1 also promotes esophageal squamous cell carcinoma (ESCC) metastasis by stabilizing the protein Snail." (PMID 39484165, 2024). "OTUB1 and OTUB2 potentiated esophageal squamous cell carcinoma (ESCC) proliferation and metastasis by regulating the stability of Snail and YAP1/TAZ proteins, respectively." (PMID 40469292, 2025). "Furthermore, USP26 108, PSMD14 121, OTUB1 117, and EIF3H 119 deubiquitinate and stabilize Snail, enhancing esophageal squamous cell carcinoma (ESCC) cell migration and tumor metastasis in vivo and in vitro." (PMID 41208892, 2025). "In esophageal squamous cell carcinoma (ESCC), DUBs such as USP26 and OTUB1 are significant regulators of the EMT, a process crucial for cancer metastasis driven by the transcription factor Snail." (PMID 39678489, 2024).
ovarian carcinoma (10 papers, 2016 to 2024). A malignant neoplasm originating from the surface ovarian epithelium. "Our study shows that OTUB1, highly expressed in ovarian cancer, binds to FOXM1 and cleaves the K48-linked polyUb chain, stabilizing FOXM1 to promote tumorigenesis and tumor progression." (PMID 27167337, 2016). "OTUB1, known as a deubiquitinases, can protect the protein from degradation and belongs to the ovarian cancer proteases family." (PMID 35681168, 2022). "In ovarian cancer, OTUB1 promoted ovarian cancer cell proliferation, invasion, and tumor growth through deubiquitination and stabilization of FOXM1." (PMID 34205406, 2021). "Together, our results underscore the clinical relevance of OTUB1 in ovarian cancer progression and suggest OTUB1 as a novel therapeutic target and prognostic biomarker for the disease." (PMID 27167337, 2016). "We explored the potential OTUB1-catalyzed deubiquitination of FOXM1, a transcription factor linked to carcinogenesis, and the biological consequence of that interaction in ovarian cancer." (PMID 27167337, 2016). "It has shown that OTUB1 could be a promising therapeutic target for protecting against DOX-induced cardiac toxicity in ovarian cancer mice." (PMID 39256355, 2024). "Moreover, OTUB1-FOXM1 interaction drives tumor progression and OTUB1 expression predicts a poor prognosis in ovarian cancer." (PMID 27167337, 2016). "Furthermore, we explored the essentiality of OTUB1-FOXM1 interaction to the biological function of OTUB1 in ovarian cancer." (PMID 27167337, 2016). "To study the biological effects of OTUB1 on ovarian cancer, we first confirmed the oncogenic functions of OTUB1 on cell proliferation in vitro, which was further identified in the in vivo xenograft models; OTUB1 also promoted cell migration and invasion in vitro." (PMID 27167337, 2016). "Moreover, elevated expression of OTUB1 predicts poor prognosis in ovarian cancer." (PMID 27167337, 2016). "To explore the correlation between OTUB1 and FOXM1 in ovarian cancer, we analyzed the immunostaining of OTUB1 and FOXM1 protein in samples from 200 ovarian cancer patients." (PMID 27167337, 2016). "Based on the relationship between OTUB1 and FOXM1, and FOXM1's enhancement of ovarian cancer chemoresistance, the effect of OTUB1 and the OTUB1-FOXM1 axis on ovarian cancer chemoresistance is a curious question for future studies." (PMID 27167337, 2016). "Next, we elucidated the clinical significance of OTUB1 and FOXM1 protein in 200 tissues of ovarian cancer." (PMID 27167337, 2016). "OTUB1 and FOXM1 expression were consistently correlated in immunoblotting results of total protein extracted from 25 ovarian carcinoma tissue samples (r=0.448, p=0.025)." (PMID 27167337, 2016). "Our results indicate that OTUB1 exerts oncogenic activities in ovarian cancer and its expression is tightly correlated with FOXM1 in human ovarian cancer samples." (PMID 27167337, 2016).
multiple myeloma (9 papers, 2020 to 2025). "As a result, inhibiting OTUB1 decreases c-Maf protein levels and causes cell apoptosis in multiple myeloma cells." (PMID 38264570, 2023). "For example, (a) Ubiquitin transfer blockade: In multiple myeloma, OTUB1 interacted with the E2 enzyme UBE2D3 to inhibit ubiquitination of the transcription factor c-Maf, stabilizing its expression and promoting tumor cell survival." (PMID 40469292, 2025). "Further, patients with high expression of OTUB1 show poor clinical outcomes in the c-MYC-dependent cancer multiple myeloma." (PMID 35159073, 2022). "In primary multiple myeloma cells, the OTUB1 transcript is expressed within the top 5% of all deubiquitinases, and in HeLa cells, its expression level ranks in the top 12%." (PMID 35159073, 2022). "Confirming its role in enhancing c-MYC activity, we found that elevated OTUB1 correlates with inferior clinical outcomes in the c-MYC-dependent cancer multiple myeloma, and overexpression of OTUB1 accelerates the growth of myeloma cells." (PMID 35159073, 2022). "We illustrate a relationship between high OTUB1 expression and decreased survival in multiple myeloma, a c-MYC-dependent cancer, and confirm the ability of OTUB1 to stabilize c-MYC in a multiple myeloma cell line." (PMID 35159073, 2022). "The present study demonstrated that AVT elicits its anti-myeloma activity via inhibiting the Otub1/c-Maf axis therefore activating apoptotic signaling transduction." (PMID 33627137, 2021). "The oncogenic transcript factor c-Maf is stabilized by the deubiquitinase Otub1 and promotes myeloma cell proliferation and confers to chemoresistance." (PMID 33627137, 2021). "As a deubiqutinase Otub1 stabilizes and promotes the oncogenic activity of the transcription factor c-Maf in multiple myeloma (MM), a malignancy of plasma cells." (PMID 32999280, 2020). "To assess whether OTUB1 has an effect as a tumor suppressor or an oncogene in multiple myeloma, we examined the survival of patients based on the expression of OTUB1 in the cancer cells." (PMID 35159073, 2022). "OTUB1 was highly expressed in primary multiple myeloma cells." (PMID 35159073, 2022). "It is also in agreement with our hypothesis that AVT inhibits the Otub1/c-Maf axis therefore leading to MM cell apoptosis and myeloma regression." (PMID 33627137, 2021). "The natural product AVT inhibits the Otub1/c-Maf axis and displays potent anti-myeloma activity." (PMID 33627137, 2021). "Finally, elevating OTUB1 expression in multiple myeloma cells stimulates more aggressive growth." (PMID 35159073, 2022). "Through similar methods, the herbal acevaltrate and anti-bacterial/anti-viral nanchangmycin have been identified to inhibit OTUB1/c-MAF axis and induce myeloma cell apoptosis." (PMID 38264570, 2023). "A screen for bioactive inhibitors of the Otub1/c-Maf axis in multiple myeloma cells demonstrated that NCMC induces c-Maf polyubiquitination and proteasomal degradation in the presence of Otub1." (PMID 35617485, 2022). "To examine whether OTUB1 expression has a physiological impact on c-MYC-addicted cancers, we analyzed its expression in multiple myeloma." (PMID 35159073, 2022). "USP5 and OTUB1 stabilize c-Maf and promote myeloma cell proliferation and survival, which indicates that USP5/c-Maf or OTUB1/c-Maf axis could be a potential target for myeloma therapy." (PMID 34454635, 2021).